FDXR (ferredoxin reductase)
Description:
Serves as the first electron transfer protein in all the mitochondrial P450 systems including cholesterol side chain cleavage in all steroidogenic tissues, steroid 11-beta hydroxylation in the adrenal cortex, 25-OH-vitamin D3-24 hydroxylation in the kidney, and sterol C-27 hydroxylation in the liver (By similarity). Also acts as a ferredoxin--NADP(+) reductase essential for coenzyme Q biosynthesis: together with FDX2, transfers the electrons required for the hydroxylation reaction performed by COQ6.
Synonyms: AR; ADXR; ADR; ANOA; MMDS9B
Tractability: Antibody: UniProt places it where antibodies can reach, with high confidence. PROTAC: ubiquitination databases record sites on it; its protein half-life has been measured.
Gene: Protein-coding gene on chromosome 17 (74,862,494 to 74,873,039, reverse strand). Ensembl gene ENSG00000161513.
Subcellular location: Mitochondrion; Mitochondrion inner membrane
Subcellular location (Human Protein Atlas): Mitochondria
Pathways (Reactome):
Metabolism: Electron transport from NADPH to Ferredoxin; Endogenous sterols; Pregnenolone biosynthesis
Disease: Defective CYP11A1 causes AICSR
Gene Ontology:
Molecular function: ferredoxin-NADP+ reductase activity; oxidoreductase activity
Biological process: ubiquinone biosynthetic process; ferredoxin metabolic process; generation of precursor metabolites and energy; steroid biosynthetic process; cholesterol metabolic process
Cellular component: mitochondrion; mitochondrial inner membrane; mitochondrial matrix
Genetic constraint (gnomAD): Loss-of-function variants: 35 observed, 51.59 expected, observed/expected ratio (o/e) 0.68, 90% interval 0.52 to 0.9. The upper end of that interval is the gene's LOEUF score, 0.9, which puts it in group 3 of 6, group 1 being the genes least tolerant of losing a copy. Missense variants: 564 observed, 618.3 expected, observed/expected ratio (o/e) 0.91, 90% interval 0.85 to 0.98. Synonymous variants: 254 observed, 251.83 expected, observed/expected ratio (o/e) 1.01, 90% interval 0.91 to 1.12.
Gene-disease validity (ClinGen):
ClinGen rates the evidence that FDXR causes each of these diseases.
FDXR-related optic atrophy mitochondrial dysfunction syndrome (autosomal recessive): Definitive. Any mitochondrial disorder in which the cause of the disease is a mutation in the FDXR gene.
Homologues: Orthologues: chimpanzee FDXR (99% identical), macaque FDXR (93% identical), pig FDXR (90% identical), dog FDXR (86% identical), guinea pig FDXR (86% identical), zebrafish fdxr (57% identical), Drosophila melanogaster dare (45% identical), Caenorhabditis elegans Y62E10A.6 (34% identical). Paralogues in human: DPYD (15% identical), DHODH (15% identical).
Diseases named in the same sentence as FDXR in open-access papers:
FDXR is named in the same sentence as 64 diseases in open-access papers, as found by Europe PMC text mining. Sharing a sentence is not in itself a finding about the gene and the disease. The quoted sentences say what the papers report.
optic atrophy (9 papers, 2019 to 2025). A disorder characterized by loss of optic nerve fibers. "The carriers of OPA3, RTN4IP1, FDXR and C12orf65 mutations in our cohort also manifested optical atrophy plus retinal degeneration." (PMID 39423307, 2025). "Recent work has identified FDXR mutations in patients with visual impairment, optic atrophy, neuropathic hearing loss, and developmental delay, resembling the global neurologic disorders seen with mitochondrial diseases." (PMID 39574227, 2025). "We now describe 2 siblings with severe biallelic FDXR mutations manifesting at birth with optic atrophy, neuropathic hearing loss, global encephalopathy, and a 46,XX androgen excess leading to variation of sex development combined with adrenal insufficiency." (PMID 38885337, 2024). "In 2017, autosomal recessive FDXR mutations were first reported in patients suffering from a potentially novel mitochondriopathy manifesting with optic atrophy and neuropathy." (PMID 38885337, 2024). "Variants in FDXR reportedly cause autosomal recessive auditory neuropathy and optic atrophy, expanding to retinal dystrophy." (PMID 37107710, 2023). "Biallelic FDXR variants are a frequent cause of congenital or early-onset severe retinal dystrophy, especially for patients with severe optic atrophy and retinal dystrophy in early childhood." (PMID 37107710, 2023). "One of the inherited mitochondrial diseases, Friedreich’s ataxia, characterized by dysregulated iron–sulfur cluster biogenesis and iron overload, shares some phenotypes with FDXR-associated disorders, including ataxia, sensory neuropathy, and optic atrophy." (PMID 37107710, 2023). "Mutations in FDXR causes sensorial neuropathies, optic atrophy, and neurodegeneration associated with inflammation." (PMID 35806169, 2022). "We identified 10 individuals from 8 unrelated families with clinical features of bilateral optic atrophy (N = 10), retinal dystrophy (N = 7), and extra-ocular findings consequent upon biallelic variants in the FDXR gene." (PMID 33938912, 2021). "Optic atrophy is one of the most striking phenotypes in human patients carrying biallelic FDXR mutations, and our analysis of the Fdxr−/− mutant mice only serves to further confirm and clarify this phenomenon." (PMID 32499495, 2020). "Our previous studies have demonstrated that hypomorphic mutations in FDXR cause a novel mitochondriopathy and optic atrophy in humans and mice, attributed in part to reduced function of the electron transport chain (ETC) as well as elevated production of reactive oxygen species (ROS)." (PMID 32499495, 2020). "In this paper, we demonstrate that FDXR mutation leads to significant optic transport defects that are likely to underlie optic atrophy, a major clinical presentation in FDXR patients, as well as a neurodegenerative loss of cells in the central nervous system (CNS)." (PMID 32499495, 2020). "Fundus changes in patients with variants in seven genes exhibited optic atrophy plus retinal degeneration in our in-house cohort, including ACO2, FDXR, NBAS, OPA3, RTN4IP1, SSBP1 and C12ORF65." (PMID 39423307, 2025). "Interestingly, FDXR-associated optic neuropathy seems to be variable and may present similar to OPA1-associated optic atrophy, Wolfram syndrome, or LHON." (PMID 33938912, 2021). "The surprising number of patient families with FDXR mutations that have been discovered in such a short period of time raises the possibility that the FDXR/FDX1/FDX2 pathway may lie behind many cases of optic atrophy and ataxia with no previously identified cause." (PMID 32499495, 2020).
breast carcinoma (7 papers, 2013 to 2025). "Ferredoxin reductase (FDXR) is a mitochondrial flavin protein that is closely involved in the occurrence and development of breast cancer." (PMID 40514365, 2025). "Specifically, we sought to ablate the endogenous mouse Fdxr gene in 4T1, a mouse mammary carcinoma cell line, and simultaneously express exogenous human FDXR protein." (PMID 41511346, 2025). "Supporting this, a recent study has shown that FDXR drives the proliferation of primary and endocrine-resistant breast cancer cells by promoting mitochondrial fatty acid oxidation through CPT1A upregulation." (PMID 39367275, 2024). "To explore the mechanism by which FDXR regulates mitochondrial function in breast cancer cells, we performed liquid chromatography (LC) tandem mass spectrometry (MS/MS)-based metabolite profiling in FDXR-knockdown (KD) T47D human ER+ breast cancer cells." (PMID 37207154, 2023). "Besides, it takes much longer time for obtaining the endocrine-resistant tumor tissues from breast cancer patients, future study will be needed to validate the roles of FDXR and CPT1A in endocrine resistance in vivo by patient-derived xenograft (PDX) models." (PMID 37207154, 2023). "Notably, FDXR expression showed a 1.6-fold increase, that is very similar to the ~1.7-fold increase reported at the same time point in four breast cancer and 8 HNSCC patients." (PMID 31632918, 2019). "Further, we showed that depletion of FDXR or FAO inhibitor etomoxir treatment reduced primary and endocrine-resistant breast cancer cell growth." (PMID 37207154, 2023). "We found that FDXR correlated with mitochondrial OXPHOS genes in the ER+ breast cancer patients, while CPT1A did not have this correlation." (PMID 37207154, 2023). "Our data showed that depletion of FDXR inhibited tumor cell growth in T47D and MCF7 breast cancer cell lines, and this phenotype could be at least partially rescued by the reconstitution of CPT1A expression." (PMID 37207154, 2023). "Also, FDXR and CPT1A did not correlated in the ER+ breast cancer patients, the reason could be that both CPT1A and mitochondrial OXPHOS genes were downstream genes regulated by FDXR, and also other factors may co-regulate CPT1A expression." (PMID 37207154, 2023).
colorectal cancer (4 papers, 2011 to 2025). A primary or metastatic malignant neoplasm that affects the colon or rectum. "Two genes (FDXR and HSP90B1) are associated with cancer: FDXR with colorectal cancer and HSP90B1 with SCLC and mesothelioma." (PMID 21489244, 2011).
Adrenal insufficiency (3 papers, 2024 to 2025). Insufficient production of steroid hormones (primarily cortisol) by the adrenal glands. "Human ferredoxin reductase variants may cause a progressive neuropathic mitochondriopathy but also can cause adrenal insufficiency and genital ambiguity." (PMID 38885337, 2024). "Thus, our work adds FDXR variants to the list of genes that may cause adrenal insufficiency and a form of syndromic 46,XX CAH featuring androgen excess." (PMID 38885337, 2024). "However, from a clinical endocrine perspective, the most remarkable feature of these reports was the absence of studies assessing clinical adrenal function or addressing the obligatory role of FDXR in steroid hormone synthesis; adrenal insufficiency had been predicted in these patients." (PMID 39574227, 2025). "We speculate that patients with less severe FDXR mutations that retain partial activity will have compensated adrenal insufficiency, as seen in the nonclassic forms of 21-hydroxylase deficiency, lipoid CAH, P450scc deficiency, and POR deficiency without ABS." (PMID 39574227, 2025). "However, given the role of FDXR in the biogenesis of steroid hormones in the adrenal gland, a concerning aspect of early-onset disease may be undiagnosed adrenal insufficiency." (PMID 39669623, 2024).
hepatocellular carcinoma (3 papers, 2022 to 2025). A malignant tumor that arises from hepatocytes.
liver disease (3 papers, 2022 to 2025).
lung carcinoma (3 papers, 2011 to 2018). "FDXR expression in lung cancer patients during radiotherapy showed an increase in FDXR expression 24 hr after the first fraction and remained significantly up-regulated for the duration of radiotherapy, 24 hr before the 5th or 6th fraction." (PMID 29330481, 2018). "Analysis of these shortest path genes indicates that some of these genes, such as ESR1, FDXR, ABCA1, IRS1, HSP90AA1, FOXM1, and IGBP1 are related to lung cancer." (PMID 23762832, 2013).
Optic neuropathy (3 papers, 2020 to 2024). "In addition to these patients with possible inherited optic neuropathies, six other patients (20.0% of patients with an alteration of the GCC) carried suspected unique pathogenic variants in six recessive genes (DPYD, AGXT, CYP1B1, ACO2, LTBP2 and FDXR)." (PMID 38796496, 2024). "The susceptibility variants identified in the other six patients were not firmly responsible on their own for a genetic form of optic neuropathy since they were found in recessives genes (DPYD, ACO2, AGXT, CYP1B1, LTBP2 and FDXR) with a single affected allele." (PMID 38796496, 2024).
prostate carcinoma (3 papers, 2018 to 2021). A carcinoma that arises from epithelial cells of the prostate gland. "Prostate cancer patients receiving radiotherapy showed an increase in FDXR expression during the course of radiotherapy, becoming significant after the 5th fraction." (PMID 29330481, 2018). "Donor samples deemed to be G2 chromosomal radiosensitive (152 abs/100 meta) were our focus, because although CDKN1A, FDXR and SESN1 were clearly radiation-responsive genes, this was consistently observed in both healthy control and prostate cancer donors." (PMID 34638945, 2021). "First, the expression profiles of five key radiation-responsive genes (FDXR, SESN1, GADD45, DDB2, and MDM2) during the course of RT in the blood of 8 prostate cancer patients treated with IMRT and SABR were analyzed." (PMID 32519025, 2020).
Retinal dystrophy (3 papers, 2021 to 2025). Retinal dystrophy is an abnormality of the retina associated with a hereditary process. "In previous studies, 47 probands have been reported to carry with biallelic pathogenic FDXR variants, with autosomal recessive optic atrophy as the main and constant presentation, while retinal dystrophy was less frequently observed." (PMID 37107710, 2023). "Overall, we report retinal dystrophy as a major clinical feature observed in patients harboring biallelic FDXR variants." (PMID 33938912, 2021). "FDXR-associated disease is a phenotypically heterogeneous disorder with retinal dystrophy being a major clinical feature observed in this cohort." (PMID 33938912, 2021). "The purpose of this study was to report retinal dystrophy as a novel clinical feature and expand the ocular phenotype in patients harboring biallelic candidate FDXR variants." (PMID 33938912, 2021). "This study describes previously unreported candidate pathogenic variants in FDXR and details the association of FDXR variants with retinal dystrophy, further expanding the clinical phenotypic spectrum consequent upon FDXR defects." (PMID 33938912, 2021). "The predominant genes for retinal dystrophy are FDXR, SSBP1, ACO2 and RTN4IP1." (PMID 39423307, 2025).
dermatitis (2 papers, 2019 to 2020). An inflammatory process affecting the skin. "In this prospective cohort study, we found that symptoms of dermatitis radiation, pain, pruritus and fatigue were associated with the expression level of some genes of the DNA-damage response pathway (FDXR, SESN1, XPC, ZMAT3, ATM, BCL2/BAX, and CDKN1A)." (PMID 31632918, 2019). "While the expression level of FDXR gene increased in patients experiencing a high grade of dermatitis radiation, those of SESN1, ATM, XPC, ZMAT3, CDKN1A genes decreased when radiation toxicity was manifested." (PMID 31632918, 2019). "Interestingly, depletion of the myelin protein zero-like 3 (MPZL3) is associated with dermatitis and alopecia in mice, and the ETC enzyme ferredoxin reductase (FDXR) sensitizes various human epithelial cell lines to ROS-induced apoptosis." (PMID 32518230, 2020).
11-beta-hydroxylase deficiency (1 paper, 2024). "In this study, participants 10 and 12 were reported to have uncontrolled hypertension, which can be reported in disorders of steroidogenesis, such as 11-beta-hydroxylase deficiency, caused by biallelic variants in the CYP11B1 gene, a downstream target of FDXR in the adrenal gland." (PMID 39669623, 2024).
acne (1 paper, 2018). An inflammatory process of the sebaceous glands which is characterized by comedones, nodules, papules and/or pustules on the skin. "Compared with normal skin, S100P and FDXR expression were significantly higher but K10 expression was slightly lower in acne lesion." (PMID 29850553, 2018). "In addition, immunostaining demonstrated overexpression of S100P and FDXR but mild downexpression of K10 in acne lesion, while ADA expression was absent in both acne lesion and normal skin." (PMID 29850553, 2018).
adrenocortical insufficiency (1 paper, 2024). An endocrine or hormonal disorder that occurs when the adrenal cortex does not produce enough of the hormone cortisol and in some cases, the hormone aldosterone. "Here, we show that biallelic FDXR variants may cause lethal adrenocortical insufficiency and a 46,XX variation of sex development." (PMID 38885337, 2024).
androgen excess (1 paper, 2024). "We investigated 2 female patients with FRM carrying the potentially novel homozygous FDXR mutation p.G437R with ambiguous genitalia at birth and sudden death in the first year of life; they presented with cortisol deficiency and androgen excess compatible with 11-hydroxylase deficiency." (PMID 38885337, 2024).
cardiomyopathy (1 paper, 2021). A disease of the heart muscle or myocardium proper. "Those authors identified genes implicated in cardiac calcium homeostasis (PDE3B), oxidative stress response (FDXR and SPATA18), and the etiology of cardiomyopathy (SGCD, BBC3 and GDF15)." (PMID 33820914, 2021).
endometrial cancer (1 paper, 2018). Primary or metastatic malignant neoplasm involving the endometrium (mucous membrane that lines the endometrial cavity). "FDXR expression in endometrial cancer patients showed a significant increase in expression in all 10 patient samples evident from 24 hr after the first fraction, detectable at later time points during the course of treatment and until its end." (PMID 29330481, 2018).
Friedreich ataxia (1 paper, 2023). An inherited condition that affects the nervous system and causes movement problems. "Antioxidants (especially idebenone), iron chelators, mitochondrial-related agents, nuclear factor erythroid-derived 2-related factor 2 activators, and gene therapy are potential treatments for Friedreich ataxia and candidates for novel therapies in FDXR-associated disorders." (PMID 37107710, 2023).
Leigh syndrome (1 paper, 2022). A progressive neurological disease defined by specific neuropathological features associating brainstem and basal ganglia lesions. "Interestingly, pathogenic variants in another iron-sulfur cluster scaffold gene, BOLA3 (MIM: 613183), and in a gene involved in iron-sulfur cluster biosynthesis, FDXR (MIM: 103270), have previously been reported to cause Leigh syndrome." (PMID 35379322, 2022).
liver cancer (1 paper, 2025). An epithelial or non-epithelial malignant neoplasm that arises from the liver. "We then examined the association of FDXR expression with these gene signatures across breast, colon, and liver cancers by performing Spearman correlation analysis using TCGA datasets." (PMID 41511346, 2025). "Similarly, FDXR was also found to be positively associated with the eight-gene signature involved in apoptosis in breast, colon, and liver cancers." (PMID 41511346, 2025). "Interestingly, we found that FDXR was positively associated with the nine-gene signature involved in DNA repair and the eight-gene signature in breast, colon, and liver cancers." (PMID 41511346, 2025).
ovarian carcinoma (1 paper, 2022). A malignant neoplasm originating from the surface ovarian epithelium. "Further, our study also found a positive correlation of ERβ and FDXR in TCGA ovarian cancer patients mRNA expression datasets." (PMID 35806169, 2022).